SMAD6 (SMAD family member 6)
Diseases named in the same sentence as SMAD6 in open-access papers (continued):
Sharing a sentence is not in itself a finding about the gene and the disease.
breast carcinoma (7 papers, 2012 to 2024). "Variants in SMAD6 have been linked with prognosis in ovarian cancer, breast cancer and pancreatic carcinoma; polymorphism in SMAD6 have also been linked with survival in NSCLC." (PMID 23284751, 2012). "We show that stable overexpression of Smad6 in breast cancer MCF10A M2 cells inhibits BMP signalling, thereby mitigating BMP6-induced suppression of mesenchymal marker expression." (PMID 27113436, 2016). "To further investigate the involvement of Smad6 in breast cancer cell invasion, we made use of multiple shRNA constructs to knockdown Smad6 in MDA-MB-231 mCherry cells." (PMID 27113436, 2016). "The clinical relevance of our findings is highlighted by the observed correlation between Smad6 expression and distant metastasis free survival specifically in ER- breast cancer patients." (PMID 27113436, 2016). "BMP signalling could be efficiently blocked by Smad6 overexpression in the ER- breast cancer cell lines that we employed." (PMID 27113436, 2016). "Since ER- breast cancer is generally more aggressive and more difficult to treat, a correlation between Smad6 expression and DMFS specifically in this subset of patients clearly demonstrates the clinical relevance of Smad6 and BMP signalling in metastasis formation in breast cancer patients." (PMID 27113436, 2016). "Except for the SMAD6 gene, other genes of the SMAD family were positively correlated in patients with breast cancer." (PMID 38514720, 2024). "SMAD4, SMAD2, SMAD3, SMAD7, SMAD1, SMAD6, and SMAD5 showed genetic variation in 1.8%, 1.2%, 1.1%, 0.8%, 0.7%, 0.6%, and 0.5% of patients with breast cancer, respectively." (PMID 38514720, 2024). "BMP7, GDF15, BMP5, SMAD6 and FSTL5 were highly expressed in the ER positive breast cancer cells (MCF-7 cells), while the expressions of TGFBR2, FSTL1 and NOG were reduced in this cohort." (PMID 37333824, 2023). "We inhibited BMP signalling specifically in the human breast cancer cell lines through stable overexpression of inhibitory Smad6 and found that Smad6, and thus the inhibition of BMP signalling, significantly enhances breast cancer cell invasion in vivo." (PMID 27113436, 2016). "Since Smad6 overexpression inhibits BMP signalling and stimulates invasion in our breast cancer cell lines, we wanted to investigate the effect of BMP stimulation on cell invasion in our zebrafish model." (PMID 27113436, 2016). "In this study, we established the involvement of Smad6, a BMP-specific inhibitory Smad, in breast cancer cell invasion." (PMID 27113436, 2016). "Using a zebrafish xenograft model, we demonstrate that overexpression of Smad6 potentiates invasion of MCF10A M2 cells and enhances the aggressiveness of breast cancer MDA-MB-231 cells in vivo, whereas a reversed phenotype is observed after Smad6 knockdown." (PMID 27113436, 2016). "Collectively, our data strongly indicates the involvement of Smad6 and BMP signalling in breast cancer cell invasion in vivo." (PMID 27113436, 2016). "In addition, SMAD3, SMAD6, and SMAD7 were lowly expressed in stage II breast cancer, while SMAD4 and SMAD2 were lowly expressed in stage III cancer." (PMID 38514720, 2024). "In all breast cancer cases, elevated levels of GREM1 and SMAD6 correlated with poor prognosis." (PMID 31694641, 2019). "However, studies further addressing the function of Smad6 in breast cancer progression in vivo are currently lacking." (PMID 27113436, 2016). "However, Smad6 can prevent the phosphorylation of other Smad members and therefore act as a negative regulator of the TGFβ mediated pathway and previous studies have shown that silencing CCN5/WISP2 expression in the breast cancer cell line MCF-7 decreases Smad6 expression levels." (PMID 29247377, 2018). "Interestingly, Smad6 and DMFS are only inversely correlated in estrogen receptor negative (ER-) breast cancers." (PMID 27113436, 2016).
Bicuspid aortic valve (6 papers, 2012 to 2025). The presence of an aortic valve with two instead of the normal three cusps (flaps). "In all three SMAD6 loss-of-function variant carriers in our study an aortic phenotype such as bicuspid aortic valve, aortic endocarditis or aortic stenosis has been identified." (PMID 40133303, 2025). "For instance, SMAD6 participates in the embryonic formation of the aortic valve, and its mutations have been found in some familial cases of the bicuspid aortic valve (BAV)." (PMID 36836489, 2023). "Both patients carrying functionally significant SMAD6 variants had bicuspid aortic valves, the commonest cardiovascular malformation, occurring in approximately 1% of the adult population." (PMID 22275001, 2012).
gastric cancer (6 papers, 2010 to 2022). A primary or metastatic malignant neoplasm involving the stomach. "On the other hand, SMAD3, SMAD5, SMAD6, and SMAD7 were associated with poor OS in the second and third stage of gastric cancer." (PMID 34138687, 2021). "Analysis showed that high expression levels of SMAD1, SMAD2, and SMAD4 are associated with a better survival rate of gastric cancer patients, whereas SMAD3, SMAD5, SMAD6, SMAD7 and SMAD9 are associated with poor prognosis." (PMID 34138687, 2021). "However, expression level of SMAD6 was significantly correlated with OS of all gastric cancer patients (HR = 1.42 (1.19–1.71), P = 0.00014 and gastrointestinal cancer patients (HR = 1.56 (1.05–2.31), P = 0.026." (PMID 34138687, 2021). "However, a potent proteasome inhibitor MG‐132 suppressed the expression Smad6 in gastric cancer TMK1 cells, which is opposite to our results." (PMID 32954678, 2020). "In addition, SMAD6 and SMAD7 were associated with poor OS in poorly differentiated gastric cancer." (PMID 34138687, 2021). "FGD5-AS1 can be used as a sponge of miR-196a-5p to upregulate SMAD6, inhibit SMAD1/5/8 phosphorylation, and participate in the TGF-β signaling pathway, thereby inducing the role of the BMP axis in the EMT process of gastric cancer cells." (PMID 35475392, 2022). "In conclusion, this research supported the first evidence that FGD5-AS1 suppressed proliferation and metastasis in gastric cancer by regulating miR-196a-5p/SMAD6/BMP axis and suggested a potential therapeutic candidate for gastric cancer." (PMID 33892661, 2021). "In mechanism, this article also investigated that lncFGD5-AS1 worked through regulating miR-196a-5p/SMAD6/BMP axis on the EMT process and served as a potential therapeutic candidate for gastric cancer." (PMID 33892661, 2021).
glioma (5 papers, 2016 to 2022). A benign or malignant brain and spinal cord tumor that arises from glial cells (astrocytes, oligodendrocytes, ependymal cells). "SMAD6 was found to be overexpressed in glioma, and its overexpression is associated with poor patient survival." (PMID 33193701, 2020). "In grade IV gliomas, high Smad6 protein expression is closely associated with poor survival outcome." (PMID 29950561, 2018). "In the present study, we observed that Smad6 levels were increased in nuclei of glioma cell and associated with poor patient survival." (PMID 29950561, 2018). "Therefore, our data suggest that the expression of Smad6 is associated with glioma tumorigenesis, especially in GBM." (PMID 29950561, 2018). "Transfection of miR-186 into human glioma cells showed increased apoptosis through direct suppression of Smad6, which was negatively regulated by miR-186 levels." (PMID 35922753, 2022). "To determine the significance of Smad6 in human gliomas, we cultured primary cells derived from patient-derived gliomas tissue resections." (PMID 29950561, 2018). "Correlation analysis indicated that Smad6 protein levels positively correlated to the proliferative ability of these patient-derived glioma cells." (PMID 29950561, 2018). "The present study found that Smad6, especially nuclear-Smad6, was highly expressed in gliomas, and elevated expression of Smad6 correlated with poor survival." (PMID 29950561, 2018). "The patient-derived glioma cells (T06) expressing high Smad6 and low PIAS3 were implanted into mouse brains." (PMID 29950561, 2018). "To further investigate the contribution of Smad6 to glioma pathology, we established a patient-derived xenograft model." (PMID 29950561, 2018). "In primary glioma cells, Smad6 was also determined to be a predominantly nuclear protein and its expression intensity is corresponding to the tumor formation capacity." (PMID 29950561, 2018). "Collectively, we conclude that nuclear-Smad6 enhances glioma development by inducing PIAS3 degradation and subsequent STAT3 activity upregulation." (PMID 29950561, 2018). "In conclusion, our results highlight key roles of nuclear-Smad6 as a new regulator of STAT3 through PIAS3 interaction in gliomas." (PMID 29950561, 2018). "It showed that PIAS3 expression inversely correlated with nuclear-Smad6 in glioma tissues (Spearman’s r = − 0.3323, P < 0.0001)." (PMID 29950561, 2018). "Here, the authors show that Smad6 expression correlates with poor survival and is overexpressed in glioma cells, and regulates STAT3 activity via negatively regulating PIAS3." (PMID 29950561, 2018). "In this study, we report that Smad6 is overexpressed in nuclei of glioma cells, which correlates with poor patient survival and regulates STAT3 activity via negatively regulating the Protein Inhibitors of Activated STAT3 (PIAS3)." (PMID 29950561, 2018). "To examine whether Smad6 contributes to STAT3 activation, we first analyzed proteins downstream of STAT3 associated with glioma stemness, including c-jun, CCND1, and Sox2." (PMID 29950561, 2018). "Taken together, these data indicate that nuclear-Smad6 promotes glioma cell growth and development." (PMID 29950561, 2018). "As Smad6 is a key protein in regulating glioma stem-like cell initiation and self-renewal, an additional concern is that MH2 protein might have inhibitory effects on cancer stem cells and reverse chemoradiotherapy resistance." (PMID 29950561, 2018). "Smad6 was primarily localized in the nuclei of normal brain and glioma tissues." (PMID 29950561, 2018). "Thus, we proceeded with an analysis of nuclear-Smad6 expression in glioma tissues." (PMID 29950561, 2018). "In light of our findings, targeting Smad6 MH2 may present a novel therapeutic approach in glioma." (PMID 29950561, 2018). "As a result, we assumed that SMAD5 and SMAD6 might affect glioma by regulating the TGFB signaling." (PMID 27716259, 2016).
glioma (continued). "Here we provide evidence to connect elevated Smad6 and low PIAS3 to constitutive STAT3 activity in gliomas." (PMID 29950561, 2018). "Immunoprecipitation (IP) experiments determined that the endogenous interaction between Smad6 and PIAS3 exists in glioma cells." (PMID 29950561, 2018). "Surprisingly, the present study also showed a positive correlation between SMAD6 and PIAS3 at mRNA level in gliomas." (PMID 29950561, 2018). "Consequently, Smad6 reduces PIAS3-mediated STAT3 inhibition and promotes glioma cell growth and stem-like cell initiation." (PMID 29950561, 2018). "Although PIAS3 is closely associated with STAT3 and Smad6 interacts to PIAS3, we did not observe direct interaction between Smad6 and STAT3 in glioma cells." (PMID 29950561, 2018). "It showed that Smad6 protein levels were substantially higher in glioma tissues from stage II/III to stage IV tissues than it in normal brains." (PMID 29950561, 2018). "CEBPB might act in glioma by regulating CCL2, CCND1, THBS1, THBS2, SMAD5, SMAD6, TGFBR2, and TCF12." (PMID 27716259, 2016).
hepatoma (5 papers, 2018 to 2023). "Despite its normal transcription level in either pathology, a recent study found the enzyme to affect invasion and metastasis of hepatocellular carcinoma via SMAD6 gene, whereas it also regulates AKT/ERK1/2 signaling critical for angiogenesis of glioblastoma." (PMID 37743473, 2023). "Conversely, the decreased levels of p‐Smad1/5/8 and Smad6 following the increased level of p‐Smad3 were abolished in the HUVECs pre‐incubated with BMP9‐overexpressing HBV‐infected hepatoma cells." (PMID 37132170, 2023). "A significant decrease in the p‐Smad1/5/8 and Smad6 levels following the increase in the p‐Smad3 level was detected in the HUVECs pre‐incubated with HBV‐infected hepatoma cells compared with those pre‐incubated with HBV‐uninfected hepatoma cells." (PMID 37132170, 2023). "In human hepatoma and renal cell lines BMP7 exposure increased SMAD6 levels, which reduced SMAD2/3-SMAD4 heteromerization." (PMID 34608249, 2021). "We also show that overexpression of SMAD6 and SMURF1 in hepatoma cells inhibited HAMP-Luc activity, while endogenous MyD88 protein expression diminished." (PMID 30234111, 2018). "Both drugs effectively decreased Smad6 expression and increased p‐Smad3‐Rho‐ROCK‐MLC signalling levels in HUVECs pre‐incubated with BMP9‐overexpressing HBV‐infected cells to a level similar to that in HUVECs pre‐incubated with HBV‐infected hepatoma cells." (PMID 37132170, 2023).
ovarian carcinoma (5 papers, 2009 to 2020). A malignant neoplasm originating from the surface ovarian epithelium. "The result of CART analysis further strengthened the crucial role of SMAD6 in influencing the risk of ovarian cancer in the study population." (PMID 21984931, 2011). "Haplotype analysis further revealed that two haplotype blocks within SMAD6 were significantly associated with decreased ovarian cancer risk, as compared to the most common haplotype." (PMID 21984931, 2011). "In gene-based analysis, SMAD6 was identified as the most significant gene associated with ovarian cancer risk." (PMID 21984931, 2011). "In this study, four polymorphisms (rs4147407, rs4075546, rs16953584, and rs4776318) in SMAD6 were found to be significantly associated with ovarian cancer risk." (PMID 21984931, 2011). "One of the major findings was the significant association of SMAD6 polymorphisms with ovarian cancer risk." (PMID 21984931, 2011). "Association between SMAD6 haplotypes and ovarian cancer risk." (PMID 21984931, 2011). "SMAD6 showed the most significant association (P = .034), suggesting that of the genes examined genetic variations in this gene had the strongest influence on ovarian cancer risk.." (PMID 21984931, 2011). "Moreover, SMAD6 was reported to be overexpressed in ovarian adenocarcinoma compared to normal ovarian tissue, and expression of BMP-2 protein has been shown to induce SMAD6 expression in ovarian cancer cells and was associated with poor prognosis." (PMID 21984931, 2011). "However, mutations in SMAD6 have been reported in human ovarian cancer." (PMID 21984931, 2011). "Our microarray results suggest that BRCA1 selectively modulates SMAD6 expression in ovarian cancer cells." (PMID 22685544, 2012). "Gene-based analysis identified SMAD6 and TGFB1 (P<0.05 for all SNPs examined in each gene using the dominant or additive model) as genes associated with ovarian cancer risk." (PMID 21984931, 2011). "Although there are no reports showing involvement of SMAD6 in ovarian cancer, the stimulation of SMAD6 by BRCA1 as observed in our study may be suggestive of cytoprotective role of SMAD6 in ovarian cancer, and thus needs further investigation." (PMID 22685544, 2012). "Polymorphism study utilizing ovarian tissues from ovarian cancer patients reveal that mutations in SMAD6 gene are unlikely to be involved in ovarian carcinogenesis." (PMID 22685544, 2012). "SMAD6 is completely different in structure from other SMAD proteins; it forms stable associations with type I receptors and works as an inhibitor.The great majority of SMAD6 gene polymorphism studies are focused on identification of associations with human ovarian cancer." (PMID 32802554, 2020). "BRCA1 may induce its cytoprotective effect via modulating the expression of both SMAD6 and FST, and in turn, may induce BMP signaling pathways, which may then inhibit or delay the progression of ovarian cancer, specifically epithelial-origin ovarian cancer." (PMID 22685544, 2012).
pancreatic cancer (5 papers, 2010 to 2021). "Our study, for the first time ascribes Smad6 a role in pancreatic cancer biology, which can be further explored for the development of novel therapeutic target." (PMID 22195733, 2011). "One of them conducted in pancreatic cancer cell line, found Smad6 and Smad7 levels to be elevated in pancreatic cancer." (PMID 22195733, 2011). "Over-expression of inhibitory Smad6 and Smad7 was described in pancreatic cancer and in pancreatic cancer cell lines." (PMID 20462450, 2010). "In addition, previous studies report that SMAD6 is highly expressed in pancreatic cancers and enhances anchorage-independent growth in pancreatic cancer cells by blocking TGF-β-mediated growth inhibition." (PMID 34848693, 2021). "There are just two reports on Smad6 expression in pancreatic cancer till date." (PMID 22195733, 2011). "We also identified different roles for Smad6 and Smad7 in influencing pancreatic cancer biology." (PMID 22195733, 2011). "Others have shown that SMAD6 and SMAD7 are upregulated in pancreatic cancer." (PMID 23049692, 2012).
aortic stenosis (4 papers, 2012 to 2025). Aortic valve stenosis is a aortic valve disease caused by the incomplete opening of the aortic valve. "Nonsynonymous variants in SMAD6 have been observed in cardiovascular malformations, such as a bicuspid aortic valve with mild aortic stenosis and aortic coarctation." (PMID 36011280, 2022). "In 2012, two missense variants in the MH2 domain of SMAD6 were identified in two patients with BAV in association with mild to moderate aortic stenosis." (PMID 28659821, 2017). "The association of SMAD6 mutations with an aortic stenosis phenotype in the patients described in this study is entirely consistent with those observations and with a similar role for SMAD6 in human cardiovascular development." (PMID 22275001, 2012). "The patient heterozygous for the p.C484F SMAD6 variant allele was found to have a bicuspid aortic valve with mild aortic stenosis and aortic coarctation at the age of 30 years in the course of investigation for hypertension, and the coarctation was repaired." (PMID 22275001, 2012). "The other functionally significant SMAD6 variant we discovered (p.P415L) was present in a patient who presented with a heart murmur at 18 months and was found to have a bicuspid aortic valve with moderate aortic stenosis." (PMID 22275001, 2012).
aortic valve disease (4 papers, 2023 to 2025). "Interestingly, not only this but also four other SMAD6 variants described in this study have been reported previously in patients with aortic valve disease albeit without PAH (ClinVar database)." (PMID 40133303, 2025).